ATAD1 (ATPase family AAA domain containing 1)
Description:
Outer mitochondrial translocase required to remove mislocalized tail-anchored transmembrane proteins on mitochondria. Specifically recognizes and binds tail-anchored transmembrane proteins: acts as a dislocase that mediates the ATP-dependent extraction of mistargeted tail-anchored transmembrane proteins from the mitochondrion outer membrane (By similarity). Also plays a critical role in regulating the surface expression of AMPA receptors (AMPAR), thereby regulating synaptic plasticity and learning and memory (By similarity). Required for NMDA-stimulated AMPAR internalization and inhibition of GRIA1 and GRIA2 recycling back to the plasma membrane; these activities are ATPase-dependent (By similarity).
Synonyms: hATAD1; FNP001; FLJ14600; Msp1; AFDC1; HKPX4; THORASE
Tractability: Small molecule: a structure with a bound ligand is known. Antibody: UniProt places it where antibodies can reach, with medium confidence; UniProt predicts a signal peptide or a membrane-spanning region; its Gene Ontology location is reachable by antibodies, with medium confidence. PROTAC: ubiquitination databases record sites on it; its protein half-life has been measured.
Gene: Protein-coding gene on chromosome 10 (87,751,512 to 87,842,355, reverse strand). Ensembl gene ENSG00000138138.
Subcellular location: Mitochondrion outer membrane; Peroxisome membrane; Postsynaptic cell membrane
Subcellular location (Human Protein Atlas): Nucleoli rim; Mitochondria
Pathways (Reactome):
Protein localization: Class I peroxisomal membrane protein import
Gene Ontology:
Molecular function: ATP hydrolysis activity; ATP binding; membrane protein dislocase activity
Biological process: extraction of mislocalized protein from mitochondrial outer membrane; learning; memory; negative regulation of synaptic transmission, glutamatergic; positive regulation of receptor internalization; regulation of postsynaptic neurotransmitter receptor internalization
Cellular component: membrane; mitochondrial outer membrane; mitochondrion; peroxisomal membrane; cytosol; postsynaptic membrane; glutamatergic synapse; postsynapse
Genetic constraint (gnomAD): Loss-of-function variants: 10 observed, 33.57 expected, observed/expected ratio (o/e) 0.3, 90% interval 0.18 to 0.5. The upper end of that interval is the gene's LOEUF score, 0.5, which puts it in group 2 of 6, group 1 being the genes least tolerant of losing a copy. Missense variants: 275 observed, 428.11 expected, observed/expected ratio (o/e) 0.64, 90% interval 0.58 to 0.71. Synonymous variants: 130 observed, 144.04 expected, observed/expected ratio (o/e) 0.9, 90% interval 0.78 to 1.04.
Homologues: Orthologues: chimpanzee ATAD1 (100% identical), dog ATAD1 (100% identical), macaque ATAD1 (100% identical), mouse Atad1 (100% identical), pig ATAD1 (100% identical), rabbit ATAD1 (100% identical), guinea pig ATAD1 (99% identical), tropical clawed frog atad1 (89% identical), zebrafish atad1b (82% identical), zebrafish atad1a (66% identical), Drosophila melanogaster Kat60 (32% identical), Drosophila melanogaster kat-60L1 (30% identical), and 3 more. Paralogues in human: SPAST (34% identical), KATNA1 (33% identical), KATNAL1 (33% identical), VPS4B (32% identical), VPS4A (31% identical), FIGNL1 (31% identical), KATNAL2 (30% identical), FIGN (26% identical), FIGNL2 (26% identical).
Diseases named in the same sentence as ATAD1 in open-access papers:
ATAD1 is named in the same sentence as 83 diseases in open-access papers, as found by Europe PMC text mining. Sharing a sentence is not in itself a finding about the gene and the disease. The quoted sentences say what the papers report.
breast carcinoma (4 papers, 1999 to 2025). "Others, including Cox8a, Ndufb8, and Atad1, which are the genes involved in oxidative phosphorylation pathway, also exhibited an opposite regulation by Srsf3 KO in our Erbb2 breast cancer and DEN-induced liver cancer." (PMID 40568073, 2025).
gastric cancer (4 papers, 2021 to 2022). A primary or metastatic malignant neoplasm involving the stomach. "ATAD1 is deleted in 4.1% of gastric cancer, a disease that causes nearly 800,000 deaths worldwide each year, therefore, we estimate that 32,000 patients die every year from ATAD1-deficient gastric cancer." (PMID 36409067, 2022). "It has been reported that circ-ATAD1 is overexpressed in gastric cancer and sponges miR-140-3p to upregulate YY1, thereby increasing cancer cell proliferation." (PMID 35505304, 2022). "Re-expression of ATAD1 in the Del(10q23) cell lines HGC27 (gastric cancer), SW1088 (glioma), or RPMI7951 (melanoma) suppressed toxicity caused by various structurally distinct proteasome inhibitors." (PMID 36409067, 2022). "The role of circ-ATAD1 in cancer biology has only been explored in gastric cancer." (PMID 35505304, 2022). "CircRNA circ-ATAD1 has been characterized as an oncogenic circRNA in gastric cancer, while its role in CRC is unknown." (PMID 35505304, 2022). "CircRNA circ-ATAD1 has been characterized as an oncogenic circRNA in gastric cancer, while its role in colorectal cancer (CRC) is unknown." (PMID 35505304, 2022). "Circ-ATAD1 has been reported to play an oncogenic role in gastric cancer." (PMID 34857012, 2021).
schizophrenia (4 papers, 2020 to 2025). A major psychotic disorder characterized by abnormalities in the perception or expression of reality. "PheWAS revealed significant associations between Atad1 and psychiatric traits, including schizophrenia." (PMID 41153356, 2025). "This suggests that Atad1 interacts, indirectly, with other genes that affect neurotransmitter systems, components, and pathways implicated in schizophrenia and other disorders." (PMID 41153356, 2025). "Psychiatric traits significantly associated with ATAD1 were schizophrenia, bipolar disorder, and depression, confirming its association with human neurodevelopmental disorders." (PMID 41153356, 2025). "Thorase variants were found in schizophrenia patients via bidirectional sequencing of exons of the gene encoding Thorase (ATAD1); another ATAD1 mutation was identified as the cause of severe encephalopathy and congenital stiffness." (PMID 37626842, 2023). "The conserved aspartate (D221) in the WD motif in the human ATAD1 is found mutated to histidine in some schizophrenia patients." (PMID 31999255, 2020). "Recent studies have identified ATAD1 variants in the postmortem brains of schizophrenia patients." (PMID 41153356, 2025). "Furthermore, analysis of exome sequencing data from patients with familial neurodegenerative disorders, including schizophrenia and encephalopathy, has uncovered a strong relationship between ATAD1 mutations and these diseases." (PMID 39795902, 2024). "Analysis of a human RNA-seq dataset revealed differential expression of Atad1 between schizophrenia patients and the control group." (PMID 41153356, 2025). "Future studies should further characterize the role of Atad1 in PPI, schizophrenia, and related phenotypes, i.e., ATAD1 has been associated with hyperekplexia, a phenotype associated with “exaggerated” startle and excessive stiffness." (PMID 41153356, 2025). "Of the 10 potential candidate genes, 3 genes (Atad1, Cdc37l1, and Prkg1) were differentially expressed between schizophrenia patients and the control group." (PMID 41153356, 2025). "Finally, using an RNA-seq dataset, we found differential expression of ATAD1, including two other candidates, CDC37L1 and PRKG1, between schizophrenia and control groups, suggesting that examination of co-regulation of Atad1 and other “players” is warranted." (PMID 41153356, 2025). "There is mounting evidence that Atad1 plays a significant role in schizophrenia-related traits." (PMID 41153356, 2025). "Human mapping studies have not implicated ATAD1 in schizophrenia and related disorders; however, this gene has been implicated in neuronal function, synaptic organization, and transmission, among others." (PMID 41153356, 2025).
colorectal cancer (3 papers, 2008 to 2023). A primary or metastatic malignant neoplasm that affects the colon or rectum. "Recently, several research groups have found that circRNA circ-ATAD1 (Thorase) plays a vital role in both solid tumors (such as gastric cancer, colorectal cancer and endometrial cancer) and blood tumors (such as acute myeloid leukemia)." (PMID 37626842, 2023).
prostate adenocarcinoma (3 papers, 2022 to 2023). "Multi-omics results showed that downregulation of ATAD1 was a clinical biomarker for the pathological diagnosis and prognosis of prostate adenocarcinoma patients." (PMID 37626842, 2023). "Because the PTEN and ATAD1 genes are adjacent on human Chr10q23.31 (Poluri and Audet-Walsh, 2018), we assessed whether ATAD1 is co-deleted with PTEN using immunohistochemistry on prostate adenocarcinoma tumors." (PMID 36409067, 2022).
prostate carcinoma (3 papers, 2022 to 2023). A carcinoma that arises from epithelial cells of the prostate gland. "This ranks second only to prostate cancer in terms of the number of deaths attributable to ATAD1-deficient tumors." (PMID 36409067, 2022). "(D) Kaplan-Meier curve of overall survival from patients with metastatic, castrate-resistant prostate cancer (mCRPC), stratified based on tumor genotype at the ATAD1 and PTEN loci, with accompanying table below." (PMID 36409067, 2022). "Previous trials of proteasome inhibitors in unselected patients with prostate cancer have shown activity in a subset of patients, consistent with the possibility that this subset was enriched for patients with ATAD1-null tumors." (PMID 36409067, 2022). "Altogether, ATAD1 is deleted at a high frequency across many tumor types, including in more than 25% of prostate cancer, 11% of melanoma, 7% of glioblastoma, and 4% of gastric adenocarcinoma." (PMID 36409067, 2022). "We next used the PC3 prostate cancer cell line, which is PTEN-null and has a partial deletion of ATAD1." (PMID 36409067, 2022). "To address this, we examined the interactivity between the ATAD1 promoter and ERG by accessing the GSE55062 dataset that conducted chromatin immunoprecipitation (ChIP) assay in human prostate cancer cell line VCaP." (PMID 36362897, 2022). "Given the lack of available prostate cancer cell lines that harbor Del(10q23), we used a gastric adenocarcinoma cell line, HGC27, which is ATAD1 and PTEN deficient." (PMID 36409067, 2022).
Encephalopathy (2 papers, 2024 to 2025). Encephalopathy is a term that means brain disease, damage, or malfunction. "Accordingly, pathogenic autosomal recessive mutation of ATAD1 results in a form of hyperekplexia (HKPX4, Mendelian inheritance in man (MIM) #618011), a severe encephalopathy characterised by extreme hypertonia, respiratory failure and early-onset refractory seizures." (PMID 40857737, 2025).
glioma (2 papers, 2022 to 2024). A benign or malignant brain and spinal cord tumor that arises from glial cells (astrocytes, oligodendrocytes, ependymal cells). "In summary, ATAD1_si3 and ACBD5_si3 transfection inhibited U251 cell proliferation, suggesting that ATAD1 and ACBD5 play an oncogenic role in glioma." (PMID 38406287, 2024). "Finally, CCK8 and flow cytometry were used to explore the biological function of ATAD1 and ACBD5 in glioma cells." (PMID 38406287, 2024). "ATAD1 thus promotes growth of SW1088 glioma xenografts, despite not affecting their proliferation in 2D culture." (PMID 36409067, 2022). "ATAD1 was not necessary for basal tumor growth in PC3 cells, so we assessed the effect of ATAD1 on tumor growth of SW1088 cells, a Del(10q23) glioma cell line that is non-tumorigenic in SCID mice." (PMID 36409067, 2022).
melanoma (2 papers, 2022 to 2023). A malignant, usually aggressive tumor composed of atypical, neoplastic melanocytes. "Given the clinical significance of PTEN, but not the alternative target gene ATAD1 and KLLN, as well as the evidence of direct interaction between E_156 and the PTEN promoter in melanoma, we evaluated the tumor-suppressive function of E_156 in vitro." (PMID 37904237, 2023).
osteosarcoma (2 papers, 2018 to 2021). A usually aggressive malignant bone-forming mesenchymal neoplasm, predominantly affecting adolescents and young adults. "We aimed to analyze the role of circ-ATAD1 in osteosarcoma (OS)." (PMID 34857012, 2021).
Parkinson disease (2 papers, 2017 to 2025). A progressive degenerative disorder of the central nervous system characterized by loss of dopamine producing neurons in the substantia nigra and the presence of Lewy bodies in the substantia nigra and locus coeruleus. "Recent mouse studies, however, have shown that ATAD1 signaling is important in preventing α-synucleinopathy and behaviors associated with Parkinson’s Disease." (PMID 41153356, 2025).
Cognitive impairment (1 paper, 2024). Abnormal cognition is characterized by deficits in thinking, reasoning, or remembering. "This further emphasizes the importance of understanding the role of ATAD1 in mitochondrial modulation and its potential implications for cognitive impairments in neurological diseases." (PMID 39795902, 2024).
ischemic stroke (1 paper, 2022). A stroke disorder caused by obstruction of blood flow to the brain, due to thrombotic (local blood clot formation) or embolic (due to a blood clot or other material traveling from another site) event. "Further, Atad1 phenocopies Bcl2 and Bcl2l1 in the middle cerebral artery occlusion mouse model of ischemic stroke: deletion of Atad1 or Bcl2 exacerbates, and overexpression of Atad1, Bcl2, or Bcl2l1 decreases ischemic cell death." (PMID 36409067, 2022).
metastatic prostate carcinoma (1 paper, 2022). A carcinoma that arises from the prostate gland and has spread to other anatomic sites. "ATAD1 loss sensitizes PC3 xenografts to proteasome inhibition and predicts improved survival in patients with metastatic prostate cancer." (PMID 36409067, 2022).
ovarian endometrioid carcinoma (1 paper, 2025). "These analyses revealed several novel rearrangements that were predicted to result in in-frame protein fusions in ovarian endometrioid carcinomas, including ATAD1–PTEN, the neurofibromin genes NF1 and NF2, as well as cyclin-dependent and polo-like kinase (PLK) genes CDK7 and PLK5." (PMID 40981433, 2025).
prostate tumor (1 paper, 2022). "A preprint study reported that patients with ATAD1-null prostate tumor had favorable overall survival and that loss of ATAD1 in PC3 cells sensitized to the treatment of Bortezomib, while overexpression of ATAD1 developed drug resistance." (PMID 36362897, 2022).
stiff baby syndrome (1 paper, 2024). "However, it has been identified as a gene associated with the neurodevelopmental disorder stiff baby syndrome, and its role in promoting neuronal survival following injury, such as stroke, suggests that ATAD1 may contribute to the pathogenesis of neurological disorders." (PMID 39795902, 2024).
tumor (12 papers, 2016 to 2024). "Altogether, these data suggest that ATAD1 exerts a pro-survival effect in tumor cells (with ATAD1 deficiency decreasing tumor fitness and improving patient survival) in both murine xenografts and human mCRPC patients." (PMID 36409067, 2022). "Future work should also clarify whether a tumor’s tissue of origin influences the dependencies generated by ATAD1 deficiency, although our use of multiple cell lines from different tumor types suggests a phenotype with reasonably high penetrance." (PMID 36409067, 2022). "Such genes represent pathways whose inhibition could be selectively toxic to ATAD1-deficient tumor cells in a patient." (PMID 36409067, 2022). "We next tested whether deficiency of ATAD1 sensitized cancer cells to proteasome inhibition in mouse tumor xenografts." (PMID 36409067, 2022). "Paired t test analysis showed that circ-ATAD1 expression was upregulated in CRC tissues compared to non-tumor tissues." (PMID 35505304, 2022). "Considering the vital role of TME in tumor growth, spread, and escape from immune-mediated destruction, we further analyzed the relationship between ATAD1 and tumor-immune interaction." (PMID 36362897, 2022). "(B) Tumor volume over time for mice with flank xenografts of ATAD1-knockout PC3 cells treated with saline (vehicle) or 1 mg/kg BTZ." (PMID 36409067, 2022). "It was observed that circ-ATAD1 was significantly and inversely correlated with mature miR-618 across tumor tissues." (PMID 35505304, 2022). "The expression levels of circ-ATAD1, mature miR-154-5p, and premature miR-154-5p in paired OS and non-tumor tissues from 56 OS patients were determined using RT-qPCR." (PMID 34857012, 2021). "Mature miR-154-5p, but not premature miR-154-5p, was downregulated in OS tissues compared to non-tumor tissues and was inversely correlated with circ-ATAD1." (PMID 34857012, 2021). "The levels of circ-ATAD1, mature miR-154-5p, and premature miR-154-5p in paired OS and non-tumor tissues from 56 OS patients were determined by RT-qPCR." (PMID 34857012, 2021). "Circ-ATAD1 is overexpressed (p < 0.01), while mature miR-154-5p was under-expressed in OS tissues (p < 0.01) than in non-tumor tissues." (PMID 34857012, 2021). "Circ-ATAD1 was overexpressed in OS compared to non-tumor tissues and was detected in the nuclei of OS cells." (PMID 34857012, 2021). "To confirm whether ATAD1 alteration is associated with clinical outcome, we employ Kaplan–Meier analysis to examine the 5-year progression free survival rate of patients harboring altered (n = 144) or unaltered ATAD1 (n = 10,258) in the tumor tissue." (PMID 36362897, 2022). "This study explored the interaction between circ-ATAD1 and miR-154-5p in OS and showed that circ-ATAD1 was highly expressed in OS and might inhibit miR-154-5p maturation to attenuate its tumor-suppressive role in OS." (PMID 34857012, 2021). "While we cannot rule out the possibility that ATAD1 loss could be beneficial to tumor cells under some circumstances, our data clearly demonstrate its role as a pro-survival factor in cancer cells of diverse origins." (PMID 36409067, 2022). "The results showed that compared with normal tissues, the mRNA expression of five genes, ACBD5, ATAD1, DHRS4, GRHPR, and IDH1, was significantly up-regulated in tumor tissues." (PMID 38406287, 2024). "Paired CRC and non-tumor tissues collected from CRC patients (n = 64) were subjected to RNA extractions and RT-qPCRs to determine circ-ATAD1 expression." (PMID 35505304, 2022). "ATAD1 (ATPase Family AAA Domain Containing 1) plays a vital role in mitochondrial proteostasis and apoptosis activity, while its clinical value in PRAD and its impact on the tumor microenvironment (TME) remain unanswered." (PMID 36362897, 2022). "Paired CRC and adjacent non-tumor tissue samples collected from 64 CRC patients were subjected to RNA extractions and RT-qPCRs to analyze the expression of circ-ATAD1, premature miR-618, and mature miR-618 in CRC." (PMID 35505304, 2022).
tumor (continued). "In contrast, although amplification of Atad1 and Pten, as suggested by the CNV-by-exome analysis, was confirmed by ddPCR in some tumours, potential copy number losses were also observed in others." (PMID 34003256, 2021). "How can tumor cells cope without ATAD1 – and could these coping strategies become the target for new therapies?" (PMID 36409067, 2022). "For example, we found that ATAD1, TBC1D9, and TNNC2 expression are all mediated by transcription factors ACTRT2, MMP23B, and TP73 and methylation sites around MMP23B and TP73; these transcription factors have known functions in tumor suppression or proliferation." (PMID 33684137, 2021). "Chi-squared analysis showed that circ-ATAD1 expression in CRC tissues was closely correlated with patients’ clinical stages and tumor size, but not with patients’ age, gender, tumor location, and distance tumor metastasis." (PMID 35505304, 2022). "For each cancer type, we searched for matching gene expression and copy number datasets of at least three patients carrying homozygous deletions of these four genes (PAPSS2, ATAD1, KLLN, and PTEN) without considering other factors, such as tumor grade, age, or gender of the patients." (PMID 37984988, 2024).